EPO (erythropoietin)
Diseases named in the same sentence as EPO in open-access papers (continued):
Sharing a sentence is not in itself a finding about the gene and the disease.
Alzheimer disease (continued). "In line with this, a study in a mouse model of Alzheimer’s disease found increased cerebrocortical EPO following normobaric intermittent hypoxia with 10 cycles of 10% O2 and normoxia, administered for one hour daily repeated over 2–3 weeks, compared to normoxia-treated mice." (PMID 38137096, 2023). "In an Alzheimer’s Disease in vitro model, EPO administration could counteract the oxidative stress and consequent apoptosis in PC12 cells damaged by soluble oligomers of Aβ peptide." (PMID 33467745, 2021). "The inclusion of HCRT and EPO informatics would suppress the correlation to R2 values of 0.973 (N = 9) and 0.927 (N = 8), respectively, suggesting that HCRT drugs could be a better choice for treating Late-onset Alzheimer's disease as compared to EPO drugs." (PMID 23662159, 2013). "One therapeutic agent that may provide protection against both Alzheimer's disease and microglial injury is the cytokine and growth factor erythropoietin (EPO)." (PMID 22388478, 2012). "Our data may foster development of novel strategies to use cytoprotectants such as EPO for Alzheimer's disease and other degenerative disorders." (PMID 22388478, 2012). "Measurements of endogenous levels of EPO in CSF of patients with neurodegenerative diseases has revealed EPO in CSF of patients with ALS to be lower than in controls whereas patients with Alzheimer disease (AD) or vascular dementia had EPO levels comparable to control persons." (PMID 20142991, 2009). "Finally, a limitation of our study is that we did not identify with biomarkers participants with underlying Alzheimer’s disease and that we did not have availability of a direct measurement of EPO or ferritin in the brain." (PMID 35462689, 2022). "(iv) Anti-TfR mAb, when fused to erythropoietin, significantly lowered cortical and hippocampal Aβ peptide levels, decreased hippocampal synaptic loss, decreased cortical microglial activation, and improved spatial memory in an APP/PS1 mouse model of Alzheimer’s disease (AD)." (PMID 35884906, 2022). "Furthermore, identification of microglial cytoprotective pathways for entities such as EPO and Wnt1 may synergistically enhance the development of treatments for Alzheimer's disease." (PMID 22388478, 2012). "Erythropoietin (EPO), a hematopoietic neurotrophin, is a potential therapeutic for Alzheimer’s disease (AD) but has limited blood–brain barrier (BBB) permeability." (PMID 37111315, 2023). "HIF-1α and EPO receptor proteins are elevated in the hippocampus of patients with Alzheimer’s disease along with a decrease in GLUT1, GLUT3, and EPO protein." (PMID 35159233, 2022). "This is in line with the findings that EPO enhances LTP and memory functions in naive rats and improves memory function in a model of Alzheimers disease and long-term spatial memory deficits and brain injury following neonatal hypoxia-ischemia in rats." (PMID 23497299, 2013). "EPO and the EPOR are expressed in experimental models of Alzheimer’s disease during aging and in renal tubular cells during high glucose-induced oxidative stress." (PMID 23109841, 2012). "For example, erythropoietin (EPO) is upregulated by HIF-1α to boost erythropoiesis under anemic conditions or at high altitudes, while hypoxia exacerbates memory deficits in Alzheimer’s Disease (AD) mouse model by upregulating BACE1." (PMID 37089693, 2023). "EPO releasing cells such as Er-NPC promoted neural repair and recovery of function in a mouse model of spinal cord traumatic injury, and EPO improved memory and spatial learning in a rat model of Alzheimer’s disease." (PMID 33909634, 2021). "Also in Alzheimer's disease, which has a broad overlap with the pathomechanism of the PKD rat, a positive effect of EPO on the neurovascular unit is described." (PMID 25013951, 2014).
Alzheimer disease (continued). "The TREM2 and TYROBP mRNAs reported recently in Late-onset Alzheimer's disease also yield a correlation of R2 of 0.999 (N = 6) using similar informatics analysis, but HCRT informatics inclusion would suppress the correlation slightly as compared to the EPO informatics inclusion." (PMID 23662159, 2013).
Insulin resistance (33 papers, 2013 to 2025). Increased resistance towards insulin, that is, diminished effectiveness of insulin in reducing blood glucose levels. "In haemodialysis patients, insulin resistance correlates with deficient erythropoietin (EPO) and 1,25 dihydroxycholecalciferol [1,25(OH)2D3]." (PMID 40725208, 2025). "We hypothesized that EPO ameliorates insulin resistance and associated vascular/renal inflammation via STAT3 activation." (PMID 40943240, 2025). "Other EPO associated metabolic activity can also affect insulin resistance." (PMID 32038269, 2019). "EPO administration in high-fat diet-fed mice improved glucose metabolism and insulin resistance, mediated in part by PPARγ and SIRT1 activity and the PI3K/AKT pathway in the liver." (PMID 39996752, 2025). "Whereas some previous studies have shown that EPO and EPO-derived peptides improve insulin resistance, they used high-fat diet-induced obese animals." (PMID 40943240, 2025). "Further investigations with more observations of vascular injury and the mechanisms of anti-inflammatory effects of EPO are needed in a model of insulin resistance." (PMID 40943240, 2025). "Future additional studies will strengthen the possibility of drug-repositioning of EPO from renal anemia to a comprehensive therapeutic agent for insulin resistance." (PMID 40943240, 2025). "In conclusion, EPO improved glucose tolerance and vascular and renal inflammation in the setting of insulin resistance." (PMID 40943240, 2025). "Sucrose (12%) was given in drinking water for 10 weeks to induce insulin resistance, and EPO (75 U/kg, 3 times/week) was administered subcutaneously for the last 4 weeks." (PMID 40943240, 2025). "Responses to the oral glucose tolerance test and values of the homeostatic model assessment for insulin resistance indicated that EPO improved insulin resistance in sucrose-treated rats." (PMID 40943240, 2025). "Insulin resistance can exacerbate inflammation and oxidative stress, further impairing EPO signaling." (PMID 39518373, 2024). "There is also a link between lipid metabolism and insulin resistance, which can also impact EPO responsiveness." (PMID 39518373, 2024). "These cytokines play a critical role in insulin resistance, vascular complications, decreasing erythropoietin production and efficiency, and promoting apoptosis of immature RBCs, causing a further deficiency of circulating RBCs." (PMID 37163539, 2023). "EPO and darbepoetin alpha improved glucose tolerance and insulin resistance, inhibited lipid accumulation in the liver and white adipose tissue, and reduced body weight." (PMID 34281163, 2021). "Conversely, EPO reduces insulin resistance and increases glucose uptake in adipocytes through the activation of AKT and STAT5." (PMID 34281163, 2021). "Data on maternal insulin resistance, fetal C-peptide, erythropoietin, and inflammatory markers would add significantly to the knowledge about the specific intrauterine stimulus downregulating MME and should be included in further studies." (PMID 32012940, 2020). "Here, we report for the first time that EPO treatment enhances hepatic AKT pathway activity to improve insulin resistance via a PPARγ-dependent mechanism." (PMID 26643367, 2015). "Our findings are the first to demonstrate that EPO improves hepatic insulin resistance via PPARγ-dependent AKT activation." (PMID 26643367, 2015). "Our results revealed that EPO/EPOR upregulates PPARγ expression to alleviate insulin resistance in hepatocytes." (PMID 26643367, 2015). "This study showed for the first time that EPO attenuates insulin resistance and vascular and renal inflammation and that EPO might be a potential therapeutic tool for patients with insulin resistance." (PMID 40943240, 2025). "The present study investigated whether EPO would improve insulin resistance and vascular and renal injury in chronic sucrose treatment-induced insulin resistant model rats." (PMID 40943240, 2025).
Insulin resistance (continued). "The present study, taken together with the previous report, suggests that EPO could improve insulin resistance by activating the hepatic STAT3 pathway." (PMID 40943240, 2025). "The present study investigated whether EPO improved insulin resistance in the high-sucrose-induced insulin resistance model rats and whether EPO improved vascular and renal injury." (PMID 40943240, 2025). "In a mouse model of non-alcoholic fatty liver disease, EPO administration reduced body weight, reversed glucose intolerance and insulin resistance, reduced lipid accumulation in the liver and WAT, suppressed lipid synthesis genes in the liver, and increased lipolysis proteins in adipose tissue." (PMID 39996752, 2025). "High Hb levels in CHB patients, as observed in other studies, may be due to chronic inflammation, insulin resistance, and hypoxia-induced erythropoietin production." (PMID 39200880, 2024). "Thus, the elevation of pro-inflammatory cytokines plays an essential role in the development of insulin resistance as well as the changes in the sensitivity of progenitors to erythropoietin (erythroid growth factor)." (PMID 35895700, 2022). "Interestingly, hemodialysis patients on short-term EPO treatment showed improved glucose metabolism indicated by a reduction in insulin resistance and decreased glycated hemoglobin and hyperleptinemia." (PMID 32038269, 2019). "Since the FGF21’s improvement of insulin resistance is largely attributed to enhanced insulin action in the liver, we suggest that the EPO’s enhancement of BAT derived-FGF21 secretion contributes to the reduction of gluconeogenesis of liver in induced obese mice on a high-fat diet." (PMID 28288167, 2017). "EPO also has beneficial effects on glucose metabolism and insulin resistance." (PMID 26643367, 2015). "Insulin resistance and secondary hyperinsulinemia could however also directly lead to higher red blood cells, since insulin and erythropoietin have synergistic effects in stimulating erythroid colony proliferation." (PMID 25000394, 2014). "Interestingly, treatment with EPO has been shown to ameliorate insulin resistance in patients, who have end-stage renal disease (ESRD) and undergo hemodialysis therapy." (PMID 23326455, 2013). "Therefore, even after the establishment of insulin resistance, EPO can still activate the PI3K/Akt pathway and inhibit gluconeogenesis, regulating glucose homeostasis." (PMID 23326455, 2013). "Based on these findings, we hypothesized that macrophage M1 < M2 polarization is related to the EPO-induced renoprotective effects in sucrose-induced insulin resistance model rats and found that EPO decreased the M1 marker TNFα and increased the M2 markers Arg1 and IL10 in the kidney." (PMID 40943240, 2025). "Hence, our findings may provide new insights into the mechanisms by which EPO regulates glucose tolerance and insulin resistance." (PMID 23326455, 2013). "Erythropoietin treatment (EPO) reduced body weight and HOMA-IR (index of insulin resistance), and reduced white fat accumulation in high-fat diet (HFD)-induced obese mice in our study." (PMID 28288167, 2017). "We also observed that fasting glucose levels did not rise up to the level seen in control wild-types in EPO Tg pigs before or after HF-diets, implying mitigation of insulin resistance." (PMID 30834158, 2019). "Erythropoietin (EPO) has beneficial effects on glucose metabolism and insulin resistance." (PMID 26643367, 2015). "Lack of EpoR in nonhematopoietic tissues did in no way impair the efficacy of hypoxia and rhEPO to ameliorate hyperglycemia, glucose intolerance, and insulin resistance, clearly implicating that direct EPO action on nonhematopoietic tissues was not required for glucose lowering." (PMID 40238885, 2025).
Insulin resistance (continued). "In obese C57BL/6 male mice, short term EPO treatment (2 weeks) increases hematocrit without affecting body mass, improves glucose tolerance and insulin resistance, and shifts the inflammation of white adipose tissue associated with high fat diet feeding toward an anti-inflammatory phenotype." (PMID 32038269, 2019). "Furthermore, EPO transgenic mice display significantly lower levels of blood glucose, insulin and HA1C, and are resistant to high fat diet (HFD)-induced glucose intolerance and insulin resistance." (PMID 23326455, 2013). "Therefore, studies into the effects of EPO in a non-obese model with insulin resistance are needed." (PMID 40943240, 2025). "The variation might be attributed to the majority of participants in this were diabetics without inherent complications in which, patients who have insulin resistance with a decrease in excretion of substances due to the reduced effects of insulin action, in turn, a mild effect on erythropoietin." (PMID 35377899, 2022). "Given that EPO treatment inhibits the NF-κB, ERK and JNK activation, and TNF-α and IL-6 production in animal models of hepatic injury, we hypothesize that EPO may also inhibit the HFD-induced chronic inflammation, contributing to the improvement of glucose intolerance and insulin resistance." (PMID 23326455, 2013). "Collectively, our data indicated that EPO treatment for two to five weeks could upregulate PPARγ to activate the PI3K/AKT pathway and thus alleviate hepatic insulin resistance without inducing hepatic lipid deposition." (PMID 26643367, 2015).
myelodysplastic syndrome (33 papers, 2007 to 2025). A clonal hematopoietic disorder characterized by dysplasia and ineffective hematopoiesis in one or more of the hematopoietic cell lines. "This prospective observational study aimed to verify the efficacy of erythropoietin zeta in the treatment of patients with low-risk myelodysplastic syndrome." (PMID 35329991, 2022). "The hypomethylating agents (HMAs) azacytidine (AZA) and decitabine (DAC) are usually administered after the failure of erythropoietin-stimulating agents for lower-risk myelodysplastic syndromes (LR-MDS)." (PMID 33818418, 2021). "Only if patients are refractory to enzyme therapy, perhaps in association with other conditions such as myelodysplastic syndrome, should EPO be considered and then only following measurement of endogenous EPO levels." (PMID 17655728, 2007). "EPO is a glycoprotein produced by the kidneys that primarily promotes hematopoiesis and can be used as an adjunct diagnostic tool for conditions such as renal anaemia, aplastic anaemia, and myelodysplastic syndromes." (PMID 40951886, 2025). "Erythropoietin (EPO) levels are known to be elevated in myelodysplastic syndrome and hematologic malignancies, but decreased in chronic benign anemia." (PMID 37741889, 2023). "Moreover, proinflammatory proteins S100A9 and TNFα suppress EPO expression e.g. in myelodysplastic syndrome." (PMID 34565332, 2021). "Previous studies have demonstrated that GDF11 has a critical role in normal erythropoiesis as well as the pathology of β-thalassemia, myelodysplastic syndrome (MDS), and erythropoietin-resistant anemia in hemodialysis (HD) patients." (PMID 29113418, 2017). "According to her medical history, she was diagnosed with a myelodysplastic syndrome (MDS) 8 years ago, which was effectively managed with erythropoietin." (PMID 27504121, 2016). "IL-1, IL-6, and TNF were recently shown to promote deregulation of erythropoietin with resultant anemia in acute myelogenous leukemia (AML) and myelodysplastic syndromes (MDS)." (PMID 26538823, 2015). "UEA prevalence was similar to that reported in other studies, and since this was an exclusion criterium, the heterogeneity of etiologies not measured was high (rare hematopoietic disorders, myelodysplastic syndromes, blunted erythropoietin response, etc.)." (PMID 34836070, 2021). "Moreover, in patients suffering from myelodysplastic syndromes (MDS), the effect of EPO was also age-dependent." (PMID 34440909, 2021). "Activins are members of the transforming growth factor (TGF)-β superfamily that inhibit the differentiation of late-stage erythrocyte precursors in a mechanism independent of erythropoietin and are overexpressed in myelodysplastic syndromes (MDS) and in MF." (PMID 31583083, 2019). "The use of EPO in combination with G-CSF has been reported to synergistically improve erythroid responses in a group of patients with myelodysplastic syndromes who did not respond to EPO treatment alone; however, the mechanism remains unclear." (PMID 29720275, 2018).
dyslipidemia (32 papers, 2009 to 2025). "Serum EPO has been reported as increased in older age48 and in association with components of metabolic syndrome, which has been associated with late AMD49." (PMID 29391474, 2018). "In contrast to the other components of the metabolic syndrome, which are positively related to EPO, cholesterol levels are negatively associated." (PMID 25915923, 2015). "Erythropoietin levels are positively associated with the components of the metabolic syndrome, except cholesterol." (PMID 25915923, 2015). "These circulating cytokines may operate in a more sophisticated pathophysiologic network, causing erythropoietin resistance, hypoalbuminemia, frailty, atherosclerosis, and dyslipidemia." (PMID 22935561, 2012). "It has also been shown that EPO levels are higher in subjects with metabolic syndrome as well as in individuals with abdominal obesity component." (PMID 38696124, 2024). "Previous studies had described elevated haemoglobin, ferritin and erythropoietin concentrations in humans with metabolic syndrome, and studies with obese and overweight dogs also support the possible existence of tissular hypoxia in obese dogs." (PMID 37505862, 2023). "They showed that individuals with metabolic syndrome had elevated Hb, ferritin, erythropoietin, and haptoglobin concentrations." (PMID 36361221, 2022). "We identified higher endogenous EPO levels to be positively correlated with the components of the metabolic syndrome." (PMID 25915923, 2015). "The components of the metabolic syndrome, waist circumference, glucose and blood pressure are related to high EPO levels." (PMID 25915923, 2015). "Likewise, both groups (II & III) show a significant (p < 0.05) decline in A.I compared to group I. This improved dyslipidemia suggests that EPO-based SDs have the potential to overcome severities, even those prompted by the simultaneous consumption of DRF." (PMID 35455489, 2022). "Given that EPO has been used in humans, EPO or new EPOR agonists may be valuable for the intervention of glucose intolerance-related metabolic syndrome and T2D." (PMID 23326455, 2013). "Although the strategies used in this study show that haematological and metabolic effects of EPO cannot be separated, they open a new avenue for the development of EPO versions to counteract metabolic syndrome without exacerbated and undesired hematocrit increase." (PMID 19521513, 2009). "Therefore, EPO might not be related to the metabolic syndrome solely by hypoxia, but maybe by extra-hematopoietic pathways too." (PMID 25915923, 2015).